RPS24 (ribosomal protein S24)
Diseases named in the same sentence as RPS24 in open-access papers (continued):
Sharing a sentence is not in itself a finding about the gene and the disease.
hypertrophic cardiomyopathy (1 paper, 2025). A condition in which the myocardium is hypertrophied without an obvious cause. "al., identified RPS24 and PFDN5 as key hub genes that are dysregulated in hypertrophic cardiomyopathy samples compared to healthy controls." (PMID 40382596, 2025).
type 2 diabetes (1 paper, 2024). "We found potential genetic biomarkers for MCI in patients with type 2 diabetes using WGCNA combined with the LASSO algorithm and further screened four genes, COX7C, SNRPG, TOMM7, and RPS24, which are associated with the occurrence of type 2 diabetes." (PMID 39452046, 2024). "In addition, we verified that four of these genes (COX7C, SNRPG, TOMM7, and RPS24) are also able to predict the risk of type 2 diabetes and can be used as key genes in type 2 diabetes and MCI." (PMID 39452046, 2024). "The ROC curve was screened by integrating the GEO database, and revealed COX7C, SNRPG, TOMM7, and RPS24 as key genes in the progression of type 2 diabetes." (PMID 39452046, 2024). "The t-test results showed that the expression levels of four genes (COX7C, SNRPG, TOMM7, and RPS24) were significantly different between the type 2 diabetes and control groups (p < 0.05)." (PMID 39452046, 2024). "Furthermore, RPS24 is expected to become a new biomarker for screening patients with type 2 diabetes who are more likely to progress to MCI and guide clinical treatment." (PMID 39452046, 2024).
tumor (10 papers, 2016 to 2025). "A univariate analysis showed that RPS24, the T stage, M stage, pathological stage, and tumor status were associated with OS." (PMID 36614249, 2023). "Different RPS24 isoforms have tissue-specific expression and some have been linked to tumor progression; however, the functional differences between the encoded proteins remain unclear." (PMID 34763716, 2021). "(B–C) Kaplan-Meier plots showing data from TCGA PRAD cohort of percentage of tumours that are free of biochemical recurrence versus time in years, associated with expressing the alternative splice isoforms of (B) RPS24 exon 5 (PSI cut off 0.44), and (C) FLNB exon 30 (PSI cut off 0.78)." (PMID 31478829, 2019). "Taken together, these findings suggest that RPS24 plays a significant role in determining the tumor immune status." (PMID 36614249, 2023). "qRT-PCR confirmed that RPS24 expression in HCC tissues was observably higher than that in the adjacent non-tumor tissues (cohort 1)." (PMID 36614249, 2023). "Here, the data mining of the TCGA dataset revealed that there was a high expression of RPS24 in 23 tumor tissues compared with para-cancerous tissues, especially in the case of HCC." (PMID 36614249, 2023). "The 40S ribosomal protein S24 (RPS24), one of the ribosomal proteins, significantly drives tumor occurrence and development." (PMID 36614249, 2023). "Moreover, a high expression of RPS24 is associated with various clinical parameters of the patients, such as AFP and the tumor size, and a poorer prognosis." (PMID 36614249, 2023). "In addition to protein synthesis, RPS24 has role in tumor biology that has been neglected in research." (PMID 36614249, 2023). "However, the central signaling mechanism exerting the pro-cancer function of RPS24 in the tumor cells was unclear." (PMID 36614249, 2023). "RPS24 might affect tumor progression by regulating the biological behavior of cancer cells and the immune microenvironment." (PMID 36614249, 2023). "To further verify the biological function of RPS24, we found that inhibiting the expression of RPS24 in HCC cells could inhibit the growth of subcutaneous tumor tissue in vivo." (PMID 36614249, 2023). "This suggests that RPS24 may restrict immune cell infiltration in the tumor microenvironment." (PMID 36614249, 2023). "We infer that HIVEP3, by collaborating with the ribosomal protein (RP) family, such as RPL15, RPL34, and RPS24, could regulate tumor cell cycle and apoptosis and promote tumor proliferation and infiltration metastasis, angiogenesis, or other malignant biological behaviors." (PMID 35535739, 2022). "Our experiments also demonstrated that RPS24 knockdown suppressed the growth of HCC cells and tumor proliferation of the xenograft model." (PMID 36614249, 2023). "RPS24 exon 5 (repressed by ESRP2, and overall more skipped in tumours) is skipped more in larger more advanced tumours, making the mRNA isoform associated with a decreased time to biochemical recurrence." (PMID 31478829, 2019). "The other ribosomal protein gene transcripts identified in mouse mammary gland to correlate with ZFAS1, i.e. RPS21, RPS24, RPL22 and RPL28, showed significant expression differences between normal and tumour samples (*P < 0.05, **P < 0.01, ***P < 0.001, ****P < 0.0001)." (PMID 27871336, 2016). "In addition, we discovered that highly expressed RPS24 could significantly enrich multiple cancer-promoting signaling pathways, such as the E2F targets, Wnt/β-catenin signaling, G2M checkpoint, and MYC targets, which accelerated tumor cell mitosis." (PMID 36614249, 2023).
cancer (6 papers, 2019 to 2025). A tumor composed of atypical neoplastic, often pleomorphic cells that invade other tissues. "In the case of the HALLMARK pathways, a high expression of RPS24 was associated with the activation of cancer-promoting pathways, especially in regard to cell proliferation and immune-related signaling pathways." (PMID 36614249, 2023). "Within this database, subtype-specific AS patterns were commonly found in the ribosomal protein S24 (RPS24) gene in 13 out of 24 cancer types, suggesting its potential role in cancer-specific regulation." (PMID 41258078, 2025). "Our group has further analyzed RPS24 AS isoform composition across cancer types and reported its relevance in epithelial–mesenchymal transition and response to KRAS-targeted therapy in cancer." (PMID 41258078, 2025). "Significant differences in the proportions of these RPS24 AS isoforms between cancerous and normal tissues across diverse cancer types were also observed." (PMID 38853173, 2024). "The authors wanted to understand how changes in RPS24 might affect cancer progression and treatment response." (PMID 41258078, 2025). "Furthermore, we found that the RPS24 hypermethylation or hypomethylation status affected the cancer cells’ malignant characteristics." (PMID 36614249, 2023).
RPS24 also shares sentences with these, for which no sentence is quoted: anemia (2 papers); Bloom syndrome (2); pancreatic cancer (2); Treacher-Collins syndrome (2); Werner syndrome (2); asthma (1); atrial septal defect (1); Bochdalek hernia (1); bone marrow failure (1); Bowen-Conradi syndrome (1); carotid atherosclerosis (1); cartilage-hair hypoplasia (1); childhood cancer (1); chronic myeloid leukemia (1); diabetes (1); endometrial carcinoma (1); glioblastoma (1); hypopharyngeal cancer (1); infection (1); Li-Fraumeni syndrome (1); liver cancer (1); lung adenocarcinoma (1); lymphoma (1); nasopharyngeal carcinoma (1); nerve sheath tumors (1); Obesity (1); rapadilino syndrome (1); rectum adenocarcinoma (1); Rothmund-Thomson syndrome (1); Shwachman-Diamond syndrome (1).
A further 6 diseases each share a sentence with RPS24 in 1 paper.